FGFR3 (fibroblast growth factor receptor 3)
Diseases named in the same sentence as FGFR3 in open-access papers (continued):
Sharing a sentence is not in itself a finding about the gene and the disease.
bladder cancer (continued). "In conclusion, a functional analysis of FGFR3 in bladder cancer and the tumor suppressive effect of FGFR inhibitors were confirmed in various urothelial carcinoma cell lines." (PMID 41228379, 2025). "By leveraging the urease-catalyzed decomposition of urea in urine, a persistent driving force was provided to realize the targeted delivery of anti-FGFR3 antibody in bladder cancer cells' 3D spheroids." (PMID 39896991, 2025). "Uromonitor is a urine-based biomarker test for bladder cancer recurrence detection that screens hotspot mutations in the TERT, FGFR3, and KRAS genes." (PMID 40282460, 2025). "At the genomic level, both sets of PDOs harbor common mutations associated with bladder cancer, such as PIK3CA, FGFR3, and RB1." (PMID 39921252, 2025). "This aligns with prior studies, showing that FGFR3 alterations were more prevalent in less aggressive, early-stage bladder cancers." (PMID 39410541, 2024). "Through the stimulation of the STAT3 pathway, miR181a‐5p collaborates with fibroblast growth factor receptor 3 (FGFR3) to advance bladder cancer." (PMID 38676299, 2024). "FGFR3 translocations that result in formation of oncogenic fusion proteins are found in 3–6% of bladder cancers." (PMID 39031286, 2024). "Studies in FGFR3 dependent bladder cancer cells have also showed the key role of MYC in mediating growth inhibition due to FGFR blockade." (PMID 39031286, 2024). "NEDD4 mediated PD-L1 ubiquitination and degradation and regulated T cell-induced immune surveillance in bladder cancer, which was regulated by fibroblast growth factor receptor 3 (FGFR3)." (PMID 38638430, 2024). "In addition, studies on the molecular subtypes of bladder cancer revealed that FGFR3 mutations may be associated with the luminal-papillary subtype, which itself is associated with a less aggressive phenotype and significantly longer overall survival compared with other subtypes." (PMID 38592174, 2024). "These mutations in FGFR3 lead to both increased proliferation and survival of bladder cells, making this protein not only a potent oncogenic driver in bladder cancer but also a predictive biomarker of response to FGFR3 small molecule inhibitors." (PMID 38515743, 2024). "Expression of miRs-99a/100 which target FGFR3 has been found to be inversely correlated with FGFR3 mRNA levels in bladder cancer." (PMID 39031286, 2024). "Previous research has estimated that about 50% of bladder cancers have somatic alterations in FGFR3 coding sequences." (PMID 38558536, 2024). "Prior studies examining the effect of mutant FGFR3 in bladder cancer have routinely constitutively expressed the gene transgenically under control of the Upk2 promoter." (PMID 38226620, 2024). "This is best highlighted with the switch from the FGFR3-IIIb isoform to the oncogenic FGFR3-IIIc isoform; this alternative splicing event has been shown to promote invasiveness in prostate and bladder cancers." (PMID 39195304, 2024). "Little is known about the determinants of this differential sensitivity of FGFR3 altered bladder cancer cells to FGFR inhibition." (PMID 39031286, 2024). "The activating missense mutations and in-frame FGFR3-TACC3 fusions are the most common FGFR3 alterations in advanced bladder cancer." (PMID 38255923, 2024). "Studies in bladder cancer cell lines have showed that some FGFR3 altered cell lines are sensitive to FGFR inhibition while others are moderately sensitive or resistant." (PMID 39031286, 2024). "In bladder cancer, previous reports have also observed that C > T base substitutions were most common in FGFR3 and PIK3CA." (PMID 39410541, 2024). "Blocking FGFR3 in bladder cancer with FGFR3 activation increased PD-L1 protein levels by altering its ubiquitination process, which in turn, hampered the anticancer activity of CD8+ T cells." (PMID 38638430, 2024).
bladder cancer (continued). "TERT gene promoter, FGFR3 mutations, and HER2 and HER3 mutations were recently identified as driver genetic abnormalities in bladder cancers." (PMID 38255300, 2024). "Early preclinical studies have provided evidence that FGFR3 is a valid therapeutic target in bladder cancer." (PMID 39031286, 2024). "The role of FGFR3 in urothelial bladder cancer has been thoroughly studied and the central importance of FGFR3 activation in bladder cancer pathogenesis is well established." (PMID 39031286, 2024). "In 2019, the FDA approved Erdafitinib as a treatment for locally advanced or metastatic bladder cancer with susceptible FGFR2 or FGFR3 alterations, making a profound advancement in treatment for the FGFR-altered subset of bladder cancer." (PMID 39796710, 2024). "C1GALT1 levels were consistent with FGFR3 expression levels, a specific bladder protein, in bladder cancer." (PMID 38845937, 2024). "While many genes function as drivers in several cancer types, some drivers are mutated at high frequencies only in specific tumors, such as VHL in clear cell renal cell carcinoma and FGFR3 in bladder cancer." (PMID 38890488, 2024). "Specific downstream effectors of activated FGFR3 signaling in bladder cancer have also been described." (PMID 39031286, 2024). "In 75% of non-muscle invasive bladder tumors, FGFR3 activating mutations were found, and in 50% of muscle invasive high-grade bladder cancers, FGFR3 overexpression was found." (PMID 38602556, 2024). "Gene fusions of FGFR3 with multiple partners are prevalently reported in bladder cancer, gliomas, and multiple myeloma, playing a central role in tumorigenesis and progression." (PMID 38831455, 2024). "For instance, FGFR3 activation leads to MYC expression by enhancing the MAPK pathway in bladder cancer." (PMID 39482742, 2024). "In patient MR246, who had an FGFR3 S249C-driven bladder cancer that ultimately progressed on erdafitinib, an NF2 frame­shift event was detected by ctDNA together with an FGFR2 V517M mutation." (PMID 37377403, 2023). "One study showed that suppression of FGFR3 increased PD-L1 protein levels in FGFR3-expressing bladder cancer due to influencing its ubiquitination, leading to suppression of the anticancer activity of CD8+ T cells." (PMID 37215134, 2023). "In general, operable FGFR3 gene fusion is found relatively commonly in glioma and bladder cancer, FGFR3–TACC3 fusion has been reported in 2.5% of NPC." (PMID 35377040, 2023). "As an oncogenic driver in bladder cancer, FGFR3 genomic alterations represent predictive biomarkers that predict the response to FGFR inhibitors." (PMID 37559152, 2023). "Overexpression of FGFR3 is associated with an immunologically cold, T cell-depleted phenotype, which contributes to a low ICI response rate in bladder cancer —just like a low PD-L1 expression in an FGFR3-mutant scenario." (PMID 37055532, 2023). "Currently, only limited knowledge is available regarding the phenotypic association between fibroblast growth factor receptor 3 (FGFR3) alterations and the tumor microenvironment (TME) in bladder cancer (BLCA)." (PMID 37980528, 2023). "The isoforms FGFR3b and FGFR3c have been identified in some bladder cancer cells, which bind a wide range of FGFs, including bFGF, indicating autocrine or paracrine FGFR3 signaling in some bladder tumors." (PMID 37048074, 2023). "Urine, instead, is used in a new urine-based assay to detect single mutant molecules of fibroblast growth factor receptor 3 (FGFR3) that are indicative of bladder cancer, which represents a noninvasive tool of early-stage diagnosis." (PMID 36835424, 2023). "FGFR3 fusions are relatively common in patients with glioblastomas and bladder cancer, but rarely reported in patients with lung cancer." (PMID 37493315, 2023). "Various somatic mutations of FGFR family members also lead to carcinogenesis, such as mutations in FGFR1 sequence in lung tumors and gliomas, FGFR2 in carcinomas, and FGFR3 in bladder carcinomas and multiple myelomas." (PMID 38282676, 2023).
bladder cancer (continued). "Fibroblast growth factor receptor 3 (FGFR3) up-regulation has been proposed as a promising target for bladder cancer therapy." (PMID 36675289, 2023). "According to these outcomes, FGFR3 is considered a noteworthy aim for new treatment for bladder cancer." (PMID 36765337, 2023). "One study showed that suppression of FGFR3 increased the expression of PD-L1 level via modulating its ubiquitination in bladder cancer cells, contributing to blockade of anticancer activity of CD8+ T cells." (PMID 36733484, 2023). "It is also a proven therapeutic target; the FDA has approved the use of pemigatinib, infigratinib and futibatinib for cholangiocarcinoma with FGFR2 fusions and erdafatinib for bladder cancer with FGFR2/3 fusions and FGFR3 mutations." (PMID 37980453, 2023). "Fibroblast growth factor receptor 3 (FGFR3) has been known to play a key role in bladder cancer development." (PMID 37215134, 2023). "Fibroblast growth factor receptor 3 is known as a favorable aim in vast range of cancers, particularly in bladder cancer treatment." (PMID 36765337, 2023). "FGFR3 is a transmembrane protein that is overexpressed in about 20% of advanced bladder cancers and leads to the development of aggressive tumors." (PMID 37919282, 2023). "Oncogenic FGFR3 fusions (with TACC3 as the most frequent partner gene) are found in up to 2% to 3% of bladder cancer and detected in upper tract urothelial carcinoma as well." (PMID 37377403, 2023). "Bladder cancer (BC) is one of the most prevalent malignancies worldwide and FGFR3 alterations are particularly common in BC." (PMID 37479885, 2023). "The antibody not only enables the nanomotors to actively bind to the FGFR3 antigen, which is over-expressed in bladder cancer cells, but blocks bladder cancer cell proliferation and leads to cell death." (PMID 36671940, 2023). "In light of all the studies, we can distinguish the importance of FGFR3 genetic alterations in bladder cancer." (PMID 35326568, 2022). "In this study, we started with the analysis of DEGs and DMGs generated from the comparison of the stromal composition of bladder cancer cases and found that FGFR3 has the potential to be an immune-related predictive biomarker." (PMID 35991125, 2022). "It inhibited the proliferation of bladder cancer cells overexpressing wild-type FGFR3 and demonstrated significant anticancer activity in RT112 bladder cancer xenografts." (PMID 36186578, 2022). "The objective of this study was to identify mechanisms of resistance to FGFR inhibitors in two previously uncharacterised bladder cancer cell lines harbouring FGFR3 fusions and assess rational combination therapies to enhance sensitivity to these agents." (PMID 35501832, 2022). "Most common FGFR alterations for bladder cancer, intrahepatic cholangiocarcinoma, and glioma were FGFR3 SVs (1051/7739, 13.6%), FGFR2 REs (618/6641, 9.3%), and FGFR1 SVs (239/11 550, 2.1%), respectively." (PMID 36462464, 2022). "Lately, it was indicated that FGFR3 pathways can be correlated with a poor response to immunotherapy in bladder cancer." (PMID 35326568, 2022). "The regulatory connection between miR-100 and FGFR3 has been described in osteosarcoma, bladder cancer, glioblastoma, lung cancer, prostate cancer and pancreatic cancer, but has never been reported in BC." (PMID 36615122, 2022). "We observed that the genes in the low FGFR3 expression list were strongly enriched in the biological processes associated with transplantation and cell adhesion, suggesting the possible role of FGFR3 in predicting TME metastasis status in bladder cancer." (PMID 35991125, 2022).
bladder cancer (continued). "Our findings suggest that upfront combination treatment with FGFR and ERBB3 inhibitor warrants further investigation for FGFR3-fusion driven bladder cancers." (PMID 35501832, 2022). "As known, the FGFR3 alterations were mainly enriched in the luminal bladder cancer correlated with better prognosis; specifically, the low-risk group in the present study was also observed to have more patients with FGFR3 alterations." (PMID 36033441, 2022). "In summary, we identify consistent increased activation of pERBB3 as a resistance mechanism to FGFR inhibition in FGFR3-fusion driven bladder cancer cell lines." (PMID 35501832, 2022). "In our study, we analyzed DEGs and DMGs across the stromal composition of bladder cancer cases and found that FGFR3 has the potential to be an immune-related predictive biomarker." (PMID 35991125, 2022). "In parallel, combined FGFR/ERBB inhibition further inhibited cell growth of FGFR3-fusion driven bladder cancer lines." (PMID 35501832, 2022). "In our research, we classified bladder cancer samples into a high FGFR3 expression group and a low FGFR3 expression group according to the median FGFR3 expression." (PMID 35991125, 2022). "FGFR3 gene aberrations were common in bladder cancer and FGFR3 signaling was reported to promote epithelial-to-mesenchymal transition (EMT)." (PMID 35418978, 2022). "FGFR3 SV-altered bladder cancers and FGFR1 SV-altered gliomas were significantly less likely to be TMB-high versus unaltered samples." (PMID 36462464, 2022). "Based on median FGFR3 expression, we divided all bladder cancer samples into the high-expression group and low-expression group for further analysis of the difference in infiltrated immune cells between the two groups." (PMID 35991125, 2022). "A smaller proportion of bladder cancers (3–6%) have FGFR3 chromosomal translocations which generate oncogenic FGFR3 fusion proteins." (PMID 35501832, 2022). "We demonstrate that increased expression of pERBB3 is a key mechanism of adaptive resistance to FGFR inhibitors in FGFR3-fusion driven bladder cancers, and that this also occurs rapidly following FGFR inhibitor treatment." (PMID 35501832, 2022). "We also analyzed the positional distribution of the amino acid changes of FGFR3 SVs in bladder cancer and FGFR1 SVs in glioma." (PMID 36462464, 2022). "For example, FGFR3 S249C mutation is one of the typical APOBEC mutation signature, accounting for 60% of all FGFR3 mutation profiles in the bladder cancer and UTUC." (PMID 35903294, 2022). "Follow-up investigation revealed that FGFR3, whose expression correlated inversely with cancer progression stage, appeared to be a protective factor in bladder cancer." (PMID 35991125, 2022). "FGFR3 SVs/REs were most frequent in bladder cancer (SVs: 1051/7739, 13.6%; REs: 207/7739, 2.7%) and urinary tract cancer (SVs: 116/850, 13.7%; REs: 19/850, 2.2%)." (PMID 36462464, 2022). "An important finding of the current study is the capacity of FGFR3-fusion harbouring bladder cancer cells to rapidly reactivate MAPK signalling." (PMID 35501832, 2022).
bladder cancer (continued). "A study suggested that of the most common FGFR3 mutation in about 65% of bladder cancer is caused by APOBEC, and APOBEC mutation signature plays an important biological role in bladder cancer." (PMID 35903294, 2022). "For instance, although FGFR3 is common mutation associated with the pathogenesis of both diseases, it is more frequently mutated in UTUC than in bladder cancer patients." (PMID 36547141, 2022). "Around 20% of advanced bladder cancer patients carry unfavorable genetic alterations in the fibroblast growth factor receptor 3 (FGFR3) gene." (PMID 34638374, 2021). "FGFR1 amplification has been identified in 10–20% of patients with non-small cell lung cancer whereas 4–10% of primary gastric cancers and approximately 75% of bladder cancers harbor FGFR2 amplification and FGFR3 mutations, respectively." (PMID 33898310, 2021). "As amplification/overexpression of FGFR1, FGFR2, and FGFR3 contributes to progression of lung, gastric, and bladder cancers, respectively, we verified their level of expression in all analyzed cell lines." (PMID 33898310, 2021). "A number of studies have shown that bladder cancer cells harboring FGFR3 hyperactivating mutations and FGFR3-TACC3 fusion are responsive to FGFR3 inhibition." (PMID 34638374, 2021). "The oncogenic ability of this mutation is also supported by a study in which a bladder carcinoma cell line expressing FGFR3b–Y375C lost its transforming ability upon treatment with an FGFR kinase inhibitor and/or FGFR3 shRNA." (PMID 33912469, 2021). "Continued computational modeling of bladder cancer therapy can potentially lead to patient-specific optimization of a combination of anti-FGFR3 with anti-PD-L1 treatments." (PMID 34984415, 2021). "Vofatamab or B-701 is a monoclonal antibody that targets the extracellular domain of both wild-type and mutant FGFR3 and inhibits bladder cancer cell line proliferation." (PMID 34638374, 2021). "FGFR3 inhibition has proved to be an effective strategy among other tumor types such as bladder cancer." (PMID 35127532, 2021). "In particular, FGFR3, a biomarker for prognosis of bladder cancer, was significantly inhibited in REC.BCG+ when compared with the other subtypes, supporting the aggressive characteristic of that subtype." (PMID 33535616, 2021). "Vofatamab, an anti-FGFR3 antibody, was in three phase I and phase I/II studies for bladder cancer, all of which were terminated, even though FGFR3 seems to be an interesting target, especially for NMIBC." (PMID 34123841, 2021). "At the same time, fibroblast growth factor receptors (FGFRs) have been attractive drug targets for a variety of cancers, and in 2019 the FDA approved the first therapy targeted against FGFR3 for bladder cancer." (PMID 34984415, 2021). "In fact, Kaplan–Meier survival analysis showed that when mice with FGFR3 mutant bladder cancer are treated with combination therapy, they have a much higher probability of surviving to day 25 compared to mice treated with either monotherapy." (PMID 34984415, 2021). "FGFR3 is the most frequently hyperactivated of the FGFRs in bladder cancer, and its genetic alterations are found in around 20% of advanced bladder cancer." (PMID 34638374, 2021). "Currently identified driver genetic abnormalities and signaling pathways of advanced bladder cancer include mutations in TERT gene promoter, FGFR3 mutations, and ERBB2 and ERBB3 mutations." (PMID 34638374, 2021). "FGFR3 knockdown and gene expression profiling in bladder cancer cells revealed a gene signature linking FGFR3 signaling to fatty acid synthesis." (PMID 33494394, 2021). "Targeting FGFR3 genetic aberrations with pan-FGFR inhibitors has demonstrated clinical benefits in advanced bladder cancer." (PMID 34638374, 2021).